NOTCH1 (notch receptor 1)
Diseases named in the same sentence as NOTCH1 in open-access papers (continued):
Sharing a sentence is not in itself a finding about the gene and the disease.
esophageal squamous cell carcinoma (24 papers, 2011 to 2025). Esophageal squamous cell carcinoma (ESCC) is a type of esophageal carcinoma (EC) that can affect any part of the esophagus, but is usually located in the upper or middle third. "We were initially surprised that NOTCH1 mutations were relatively infrequent in this cohort, although one previous study in esophageal squamous cell cancer had shown that NOTCH1 mutations are uncommon in Asian patients compared with matched Caucasian populations." (PMID 26395002, 2015). "Clinical evidence indicates that NOTCH1 mutation status serves as a predictive biomarker for immunotherapy efficacy in esophageal squamous cell carcinoma (ESCC)." (PMID 41050674, 2025). "We conclude that Notch1 expression is associated with cell aggressiveness and 5-FU drug resistance in human esophageal squamous cell carcinoma cell lines in vitro and is significantly associated with a poor survival in human esophageal squamous cell carcinomas." (PMID 23409141, 2013). "The regulation of Notch signaling pathway exhaustion has been reported in a variety of tumors, and previous studies have shown that Notch1 knockout plays an important role in promoting the formation of esophageal squamous cell carcinoma and immune escape." (PMID 38650927, 2024). "The analysis results of the UALCAN database showed that the expression of NOTCH1 was significantly increased in esophageal squamous cell carcinoma." (PMID 36119057, 2022). "Esophageal squamous cell carcinoma cases in the NC group were highly significantly associated with the presence of significantly mutated genes (SMGs) including KMT2D, FAT1, and NOTCH1 mutations." (PMID 36741715, 2022). "Activating the Notch1 signaling pathway, which depends on GSK3β/β-catenin, inhibited cell proliferation and induced apoptosis in the human esophageal squamous cell carcinoma cell line EC9706." (PMID 26563263, 2015). "For example, METTL3 promotes the development of esophageal squamous cell carcinoma (ESCC) through the stabilization of NOTCH1 and EGR1 mRNA, followed by activation of Notch and EGR1/Snail signaling pathways." (PMID 37965577, 2023). "Over 90% of human esophageal squamous cell carcinoma (ESCC) retain one or more wild-type copies of NOTCH1 but develop from epithelium where a high proportion of cells have biallelic NOTCH1 disruption, arguing wild-type NOTCH1 favors ESCC development." (PMID 36658434, 2023). "The role of NOTCH1 as a prognostic marker is not as clear in CRC, but in esophageal squamous cell carcinoma, it is reported to be associated with cancer progression and lower response rates." (PMID 40160429, 2025). "Moreover, Notch1 is activated in a small subset of SCC cells at the invasive tumor front and predicts for poor prognosis of esophageal SCC, shedding light upon the tumor promoting oncogenic aspect of Notch1 in SCC." (PMID 29170450, 2017).
acute myeloid leukemia (23 papers, 2012 to 2025). Acute myeloid leukemia (AML) is a group of neoplasms arising from precursor cells committed to the myeloid cell-line differentiation. "Especially, Notch1, Jagged1 and Delta1 expression might be relevant prognostic markers in intermediate risk acute myeloid leukemia." (PMID 28030808, 2017). "Notch-1 was first found to associate with hematological diseases, and its expression level increased in multiple myeloma, Hodgkin’s lymphoma, anaplastic large cell lymphoma and acute myeloid leukemia." (PMID 24423157, 2013). "Although NOTCH-1 gene mutations were reported to contributes to leukemogenesis in lymphocytic leukemias, its role in acute myeloid leukemia (AML) remains unclear." (PMID 32711424, 2020). "De-regulation of the Musashi-Numb-Notch1 signaling axis is associated with poor prognosis in CML, acute myeloid leukemia (AML) and B-cell acute lymphoblastic leukemia (B-ALL)." (PMID 24971156, 2014). "For NUMB, a potent inhibitor of NOTCH1, its expression was shown to be significantly down regulated in acute myeloid leukemia." (PMID 23300998, 2013). "Previously, we reported, based on data obtained from immunoblot analyses, that half of the samples of acute myeloid leukemia (AML) cells express Notch1 and/or Jagged1 proteins." (PMID 23181106, 2012). "While the majority of somatic mutations in NOTCH1 in T-ALL are activating and result in aberrant continued signaling, a tumor suppressor role of the Notch pathway has been shown in acute myeloid leukemia (AML)." (PMID 27590521, 2016). "Besides its contribution to myeloid development, particularly to granulocyte and macrophage differentiation and to the pathogenesis of acute myeloid leukemia (AML), miR-223 is induced by active NOTCH1 and participates in T-ALL leukemogenesis by repressing the tumor suppressor FBXW7." (PMID 36674902, 2023). "In contrast to T-ALL, Notch1 mutations are not found in B-ALL and are seen only rarely in acute myeloid leukemia (AML)." (PMID 25866806, 2015). "Within the miRNAs upregulated upon NOTCH1 inhibition, we also found significant upregulation of miR-22-3p, which has been previously reported as a putative tumor suppressor in acute myeloid leukemia (AML) but never explored in T-ALL, especially downstream of NOTCH1." (PMID 32708470, 2020).
Cerebral ischemia (23 papers, 2012 to 2025). Restriction of arterial blood supply to the brain associated with insufficient oxygenation to support the metabolic requirements of the tissue. "Some studies indicate that activating the HIF‐1α/VEGF/Notch1 pathway during cerebral ischemia treatment can promote angiogenesis and restore blood flow." (PMID 40019048, 2025). "Studies have found that during cerebral ischemia, γ‐secretase is rapidly activated, leading to an increase in Notch1 levels in the hippocampal region." (PMID 40019048, 2025). "In summary, HIF‐1α/VEGF/Notch1 levels increase following cerebral ischemia but decrease after treatment." (PMID 40019048, 2025). "The Notch1/Hes1 signaling pathway can also facilitate the growth and maturation of neural stem cells in the hippocampus of rats with cerebral ischemia, ultimately enhancing neurological function." (PMID 38891776, 2024). "Consistent with this conclusion, we found that in the acute phase in cerebral ischemia, the expression of Notch1 in the ischemic penumbra was upregulated, and this change was accompanied by extensive activation of microglia." (PMID 38137105, 2023). "Studies have shown that in the pathophysiological mechanism of cerebral ischemia, Notch1 promotes the process of pyroptosis of neurons, in addition to activating microglia and promoting the cerebral infiltration of lymphocytes." (PMID 38137105, 2023). "Taken together, LRIC promoted neurogenesis after cerebral ischemia in part by regulating the miR-449b/Notch1 pathway and, thus, plays a role in neuroprotection." (PMID 36009031, 2022). "Recent studies have shown that transcranial direct current stimulation can play a therapeutic role in inducing neurological rehabilitation through neurogenesis regulated by Notch1 signaling after cerebral ischemia/reperfusion." (PMID 35220404, 2022). "The study is also the first to demonstrate that the miR-449b/Notch1 pathway is involved in neurogenesis after cerebral ischemia." (PMID 36009031, 2022). "In this study, apoptosis and Notch1 expression in the brain tissue of CCI rats were detected, and the results show that the damages and Notch1 expression in the brain tissue changed with the prolongation of the cerebral ischemia in the Model and RT groups." (PMID 33335999, 2020). "Accordingly, the aim of this study was to investigate the neuroprotective effects of RIPC on cerebral ischemia-reperfusion injury and the roles of the Notch1 and NF-κB signaling pathways in RIPC-induced neuroprotection." (PMID 31526384, 2019). "The aim of this study was to investigate the underlying mechanism of RIPC-mediated neuroprotection against cerebral ischemia-reperfusion injury and the roles of the Notch1 and NF-κB signaling pathways in RIPC-induced cerebral ischemic tolerance." (PMID 31526384, 2019). "Activation of Notch1 signaling induced by cerebral ischemia results in a protracted nuclear factor-κB (NF-κB)-driven microglia-mediated neuroinflammation and worsens ischemic brain damage and functional outcome." (PMID 31770379, 2019). "Activation of Notch1 further promotes the increase in the p65 subunit of the NF‐κB pathway, enhancing the infiltration of inflammatory cells and the expression of inflammatory factors, thereby exacerbating neuronal damage during cerebral ischemia." (PMID 40019048, 2025). "This dynamic regulation may partially explain the seemingly paradoxical effects of HIF‐1α/VEGF/Notch1 on the pathological processes of cerebral ischemia." (PMID 40019048, 2025). "To investigate whether Notch1 in myeloid cells occupies a pivotal position in cerebral ischemia-reperfusion injury, we generated Notch1M-KO (myeloid-specific Notch1 knockout) and Notch1FL/FL mice." (PMID 38137105, 2023). "Also, overexpression of circCCDC9 inhibited apoptosis and the Notch pathway by repressing the modulator levels of Notch1, NICD, and Hes1 after cerebral ischemia/reperfusion injury in mice." (PMID 35346266, 2022).
Cerebral ischemia (continued). "However, the Notch 1 pathway, which participates in cardiac angiogenesis, can be activated by simvastatin, as has already been reported in animal models of cerebral ischemia." (PMID 32393497, 2020). "It is sure that Notch1 signaling pathway can be activated by cerebral ischemia and hypoxia." (PMID 30175143, 2018). "Therefore, we speculate that the Notch1 gene in myeloid cells plays a critical role in regulating cell pyroptosis after cerebral ischemia in mice." (PMID 38137105, 2023). "Among the Notch pathway members, the receptor Notch 1 has been shown to be expressed in the hippocampus domain of the adult brain, affecting the neural development of the hippocampus, and to be involved in the processes of angiogenesis and neurogenesis after cerebral ischemia injury." (PMID 33335999, 2020). "Here, we show that Notch signaling pathway is activated as evidenced by the up-regulation of Notch-1, NICD, RBP-JK and Hes-1 in activated microglia in experimentally induced cerebral ischemia and OGD induced activated BV-2 microglia." (PMID 28288585, 2017). "In this study, we found that RIPC could upregulate the expression of p-IKK α/β and p-NF-κB p65 while activating the Notch1 signaling pathway, suggesting that RIPC activates the NF-κB pathway in cerebral ischemia-reperfusion injury." (PMID 31526384, 2019). "Under extreme conditions of cerebral ischemia‐reperfusion, HIF‐1α is pathologically overexpressed in tissue cells, resulting in abnormal elevations of VEGF and Notch1, which may not be conducive to the protection of neural function." (PMID 39364701, 2024).
endometriosis (23 papers, 2010 to 2025). The growth of functional endometrial tissue in anatomic sites outside the uterine body. "Previous studies have shown that endometriosis is associated with a significant increase in the number of eutopic endometrial NOTCH1+ cells and CD117+ cells in comparison to a healthy control group." (PMID 39125516, 2024). "In some disorders, for example, endometriosis is associated with decreased expression of NOTCH1-regulated, FOXO1-responsive genes during decidualization." (PMID 35740346, 2022). "The involvement of ASC’s in the pathogenesis of endometriosis is further supported by increased expression of Numb and Notch1 in eutopic endometrium from patients with endometriosis, when compared with controls, and could be associated with increased severity of the condition." (PMID 30347708, 2018). "In contrast, patients with endometriosis have dysregulated UF-EV profiles marked by reduced miR-200b-3p and increased miR-145-5p levels, resulting in the inhibition of NOTCH1 and HOXA10, two genes essential for trophoblast invasion and decidualisation." (PMID 41296460, 2025). "It is possible that cooperation between CD117+ cells and Notch1+ cells contributes to the maintenance of stem cells in endometriosis lesions, similar to previous findings concerning neural stem cells." (PMID 39125516, 2024). "NOTCH1 was found to be elevated in localizations adjacent to peritoneal endometriosis implants but decreased in eutopic endometrium in endometriosis patients." (PMID 36612107, 2022). "Increased expression of MSI-1 which acts as a positive regulator of NOTCH1 was reported in endometriosis." (PMID 36612107, 2022). "Another molecule with potential implications for P4 resistance in endometriosis is Notch homolog 1 (NOTCH1)." (PMID 31387263, 2019). "Of those increased, NOTCH1 is associated with cancer metastasis though TGF-β induced EMT and EMT of endometriotic cells has recently been implicated in the development of endometriosis." (PMID 25207642, 2014). "Moreover, NOTCH1 silencing reduced FOXO1 expression more markedly in ESCs from endometriosis patients compared to controls, indicating that impaired Notch signaling contributes to decidualization defects through FOXO1 downregulation." (PMID 40072055, 2025). "Additionally, circ_0067301 and circ_0061140 can induce the expression of different members of the Notch family, Notch1 and Notch2, in endometriosis." (PMID 41283360, 2025). "In summary, both endometriosis and adenomyosis lesions contain NOTCH1+ and CD117+ stem cells." (PMID 39125516, 2024). "Notch1 activity also mediates estrogen-stimulated stromal cell invasion in endometriosis." (PMID 38999962, 2024). "Unlike adenomyosis, endometriosis lesions are associated with higher quantities of NOTCH1+ and CD117+ stem cells and a coordinated increase in their number." (PMID 39125516, 2024). "Oxidative stress in endometriosis activates NOTCH1 signaling and promotes fibrosis in implants." (PMID 36612107, 2022). "In addition, two circRNAs (circ_0067301 and circ_0061140) induced the expression of different members of the Notch family, Notch1 and Notch2 in endometriosis." (PMID 34122342, 2021). "In the pathogenesis of endometriosis, an inflammatory gynecological disease in female reproduction, the higher level of IL-6 produced by the macrophages and local epithelial cells leads to up-regulation of NOTCH1 expression and the hyper-proliferation of the ectopic tissue." (PMID 38538986, 2024). "Indeed, studies from our group have suggested a role of the notch signaling pathway in endometriosis, since notch-1 expression in endometrial glands is significantly higher in the eutopic endometrium of patients with deep infiltrating endometriosis compared with controls." (PMID 37620963, 2023). "Besides miRNAs, Notch1 signaling is also affected during endometriosis." (PMID 32183093, 2020).
endometriosis (continued). "The significantly lower numbers of NOTCH1- and CD117-positive cells in patients with adenomyosis compared with those with endometriosis point to the probability of a different pathogenetic mechanism of occurrence." (PMID 39125516, 2024). "The aim of this study was to compare the quantity of NOTCH1- and CD117-positive cells between endometriosis and adenomyosis lesions." (PMID 39125516, 2024). "The aim of this study was to investigate and compare the quantity of NOTCH1+ and CD117+ stem cells in endometriosis and adenomyosis lesions." (PMID 39125516, 2024). "The performed Spearman’s correlation test showed that there was a positive correlation between the quantities of NOTCH1+ and CD117+ cells in endometriosis lesions (R = 0.45, p = 0.027)." (PMID 39125516, 2024). "Stem cells that express specific cell markers, such as NOTCH1, CD117, OCT-4, Musashi-1, SUSD2, N-cadherin or SSEA-1, have been found in the eutopic endometrium of patients with endometriosis and adenomyosis." (PMID 39125516, 2024). "Mann–Whitney U test showed that the median percentages of both NOTCH1+ and CD117+ cells in the endometriosis lesions were significantly higher than those in the adenomyosis lesions (2.26% vs. 0.13%, p = 0.002 and 0.44% vs. 0.26%, p = 0.016, respectively)." (PMID 39125516, 2024). "Inconsistently, the current study demonstrated that NOTCH1, JAG-1, JAG-2, and survivin, as a down target molecule of NOTCH pathway, significantly decrease in women with PCOS, endometriosis, and RIF." (PMID 31168348, 2019). "qPCR analysis indicated a significant decrease in NOTCH1 mRNA expression levels of women with PCOS, endometriosis and RIF groups compared with the healthy group during the implantation window." (PMID 31168348, 2019). "In summary, we confirm that aberrant expression of Notch1/Numb signaling and an active EMT process are present in eutopic endometrium of endometriosis, and we provide an experimental basis for considering melatonin as a potential treatment for endometriosis." (PMID 29935526, 2018). "Our study also demonstrated that the percentages of NOTCH1+ and CD117+ stem cells are strongly associated with the endometriosis lesions but not in the adenomyosis lesions." (PMID 39125516, 2024). "In a recent study involving women with endometrial disorders including RIF, endometriosis, and PCOS, the expression pattern of NOTCH pathway molecules including NOTCH1, 3, JAG1, 2, and survivin in the mid-luteal phase were distinctly expressed in the patient groups compared to controls." (PMID 36776897, 2023). "In vitro reduction of NOTCH1 signaling restored PGR and P4-responsiveness, revealing a direct relationship between Notch signaling regulation and the maintenance of proper P4-responsiveness, both of which are disrupted in endometriosis." (PMID 31387263, 2019). "NOTCH1 and CREB1 were significantly increased suggesting that the peritoneum adjacent to endometriosis lesions may be more prone to undergoing TGF-β induced EMT and neurogenesis." (PMID 25207642, 2014). "In terms of endometriosis lesion subtypes, the intestinal endometriosis lesions contained the largest quantities of both NOTCH1+ (11.5 ± 7.7%) and CD117+ endometrial stromal cells (7.9 ± 6.2%), followed by the cutaneous scar (11.4 ± 4.9% NOTCH1+ and 0.48 ± 0.35% CD117+ stromal cells)." (PMID 39125516, 2024).